NOTCH4 (notch receptor 4)
Diseases named in the same sentence as NOTCH4 in open-access papers (continued):
Sharing a sentence is not in itself a finding about the gene and the disease.
tumor (continued). "This complex downregulates the expression of IL-8 and MMP-9 and elevates the expression levels of Notch 4, Ikaros, and integrin alpha-D/CD-11d (tumor-suppressive), which conjointly prevents inflammation, metastasis, and epithelial-mesenchymal transition (EMT) in CML cells." (PMID 35815090, 2022). "Taking these previous reports into accounts, we hypothesize that Notch4-meidated Pcsk5 regulation may involve cross-talk with the activin/TGFβ signaling pathways during pancreatic tumorigenesis, thus affect tumor burden and survival." (PMID 36970723, 2022). "High expression of Notch1 indicates higher differentiation, while increased expression of Notch4 may indicate a lower degree of differentiation and possibly a tumor with more aggressive function." (PMID 36643842, 2021). "In our previous study, we determined that TNBC cells with acquired RT resistance exhibited significantly increased expression levels of Notch-4, β-catenin, and Snail, which are involved in self-renewal as well as tumor progression, compared to those in the parental cells." (PMID 34502547, 2021). "Furthermore, when we re-examined our IHC staining of NOTCH4, the NOTCH4+ cells were more frequently found to localize near the interface of tumor and stroma, indicating a pro-invasion role of NOTCH4." (PMID 32104513, 2020). "The absence of Notch4 receptor in our study is in accordance with a previous study which shows reduction of Notch4, implying that Notch4 may act as a tumor suppressor gene in GBM." (PMID 30606241, 2019). "Nuclear staining for Notch4 and Survivin had significant differences between the tumor types with type II patients showing a higher percent of positive cells (Notch4: 20%, (intensity: 2-to-3+) versus 5%, (intensity: 1+); Survivin: 75% (intensity: 3+) versus 51% (intensity:1+) (p = 0.0001)." (PMID 28659656, 2017). "We observed that tumor-induced decrease in the expression of Notch receptors, Notch1, Notch2, Notch3 and Notch4, as well as ligands Dll1, Dll4 and Jagged1 in splenocytes of 4T1HA and RencaHA tumor-bearing mice could be reversed by treatment with bortezomib." (PMID 26431276, 2015). "Thus, we established, using PDX models and cell lines in tumor-initiating cell assays, that NOTCH4 inhibition reduces BCSC activity induced by anti-estrogen treatment." (PMID 26387946, 2015). "Moreover, the observed expression patterns in the microarray showed that Notch4 was overexpressed in the primary tumor tissues and lung metastasis when compared with normal tissue using a microarray platform." (PMID 26059540, 2015). "To examine a possible role for Notch4 in mammary vascular morphogenesis, we compared the vessel density in the mammary gland between wild type and Notch4−/− mice at 3 weeks of age, same age at which mice were transplanted with tumor cells." (PMID 23601498, 2013). "Surprisingly, our results indicate that Notch4 is dispensable for vessel sprouting in the tumor." (PMID 23601498, 2013). "Notch1 and Notch4 are expressed in normal and tumor lymphatic endothelial cells, and Notch1 is activated in lymphatic endothelium of invasive mammary micropapillary carcinomas These data suggest a role for cross-talk between VEGFR-3 and Notch in both tumor angiogenesis and lymphangiogenesis." (PMID 22487493, 2012). "Interestingly, tumor cells within metastatic lesions uniformly express Mmp10 and Notch4 suggesting that they are derived from, and highly enriched in, CSCs." (PMID 22545096, 2012). "Therefore it appears plausible that Notch1 is also the predominant mediator of Dll4-Notch signaling in the tumor vasculature, although Notch4 has also been described as a receptor specifically expressed by endothelial cells." (PMID 21923938, 2011). "Notch-4 has been shown to be critical for the survival of tumour-initiating cells." (PMID 21847123, 2011).
tumor (continued). "It was found that the levels of lncRNA CADM2-AS1 and NOTCH4 mRNA in GC tissues with lymph node metastasis were notably higher than that in tumor-adjacent tissues respectively, while the level of miR-5047 in GC tissues with lymph node metastasis was lower than that in tumor-adjacent tissues." (PMID 39309008, 2024). "We first assessed whether anti-Notch4 therapy could prevent tumor growth in preclinical models." (PMID 38984877, 2024). "Interestingly, the expression level of Notch4 is different in different types of tumours." (PMID 37108670, 2023). "Probably, the poor clinical prognosis in high Notch4 patients might be related to vascular mimicry (VM), which is a tumour microcirculation system imitating the layout of the embryonic vascular network to provide oxygen and nutrients to tumour cells and, importantly, is epithelium independent." (PMID 37108670, 2023). "Interestingly, our data demonstrated a similar result that Notch4 showed positive staining both in tumor cells and endothelial cells, suggesting Notch4 may play dual roles respectively in tumor cells and endothelial cells." (PMID 37284062, 2023). "Hence an alternative hypothesis would be that the inactivation of Notch4 can induce inhibition of Pcsk5 expression, resulting in impaired tumor angiogenesis and, consequently, reduced tumor burden and increased survival." (PMID 36970723, 2022). "In addition, despite the strong correlation between NOTCH4-MUT and improved tumor immunogenicity as well as inflamed antitumor immunity, it is still necessary to further explore the potential molecular mechanism by which NOTCH4-MUT sensitizes patients to ICI therapy." (PMID 34284787, 2021). "Interestingly, decreased levels of Notch4 (but not of Notch1), obtained by both RNA interference or pharmacological treatment, significantly reduced mammosphere formation in vitro and reduced tumor formation in vivo, thus suggesting a specific role of Notch4 in regulating this subpopulation." (PMID 31379945, 2019). "However, our data suggested that Notch4 might function as a tumor suppressor in lung SCC and as a tumor activator in lung ADC similar with Notch1." (PMID 30034624, 2018). "However, final tumor size was similar between tumors grown in wild type and Notch4 null hosts." (PMID 23601498, 2013). "Our work uncovers a novel role of Notch4 in the early establishment of vessel perfusion; whether this is a mechanism unique to tumor vessel angiogenesis or whether it is present also during development or in other postnatal angiogenic settings remains to be determined." (PMID 23601498, 2013). "Although we detected Notch4 overexpression predominantly in the tumor vasculature, we cannot rule out the possibility that host myeloid cells may contribute to the difference in tumor onset between the two host genotypes." (PMID 23601498, 2013). "Thus while the importance of the Dll4-Notch1 signaling axis in tumor angiogenesis is well documented, whether Notch4, primarily expressed in the endothelium, is required for angiogenesis, vascular perfusion, and tumor progression is unknown." (PMID 23601498, 2013). "Next we examined whether host Notch4 was required for tumor progression after tumor onset." (PMID 23601498, 2013). "Therefore, our results reveal that host Notch4 plays a necessary role in tumor onset." (PMID 23601498, 2013). "Interestingly, CMT167 oncosphere cultures are not only enriched in CCSP+/SPC+ cells (data not shown), but also in CD133+/Notch4+ cells, two markers implicated in both human and mouse CSCs from various tumor types including lung." (PMID 22545096, 2012). "NOTCH4 is upregulated in cSCC through the NOTCH4/HEY1 pathway, inducing tumor cell proliferation, resistance to cisplatin, and promoting epithelial-to-mesenchymal transition (EMT)." (PMID 39925808, 2025).
tumor (continued). "It was found that mRNA levels of neurogenic locus notch homolog protein 4 (NOTCH4) was obviously upregulated after lncRNA CADM2-AS1 overexpression, which is a close regulator of tumor metastasis." (PMID 39309008, 2024). "Simultaneously, increased NOTCH4 and HSPG2 signals were detected, which contribute to tumour vascular structure formation." (PMID 38778448, 2024). "Previous research showed that the knockdown of Notch4 in TNBCS suppressed cancer stem cell activity and migration, indicating that Notch4 is a potential target for tumor intervention." (PMID 37149651, 2023). "However, in terms of Retcome pathways, overexpressed GOT2 was positively associated with tumor-related pathways, such as “MTOR Signaling” (NES = 1.44, adj. p < 0.001), “Cellular Response To Hypoxia” (NES = 1.647, adj. p = 0.004), “Signaling By NOTCH4” (NES = 1.661, adj. p = 0.007)." (PMID 37693904, 2023). "Many studies have proved that the high expression of Notch4 and CDH5 is an important factor to promote tumor development." (PMID 34149795, 2021). "Notch4 inhibition also reduces the number and size of MDA-MB-231 xenograft tumour metastases in vivo, which is accompanied by restoration of E-cadherin expression, inactivation of β-catenin and downregulation of Slug." (PMID 34295896, 2021). "Mice harboring RT-R-MDA-MB-231 cell xenografts showed enhanced tumor growth and higher expression of the CSC markers, CD44, Notch-4, and Oct3/4." (PMID 33126606, 2020). "In this research, it was found that Notch4 activated STAT3 and that this pathway has induced epithelial-to-mesenchymal transition (EMT) in tamoxifen-resistant tumor cells." (PMID 32605277, 2020). "Inhibition of Notch4 by the GSI RO4929097 in vivo resulted in decreased mammospheres of tumor-isolated cells and severely restricted tumor-initiating cell frequency, using ELDA." (PMID 33003540, 2020). "The initial evidence for the pro-tumor roles of Notch family members in BC progression arose from mouse mammary tumor virus (MMTV) studies, where the insertion site for MMTV was Notch4, converting mammary epithelial cells to neoplastic cells in mice." (PMID 32605277, 2020). "To explore this possibility, we performed tumor transplantation in a serial dilution to compare the tumor formation frequency of the following BCSC enriched populations, namely ALDH+, ALDH+CD24-CD44+, CD24-CD44+, NOTCH4+ and CD24-CD44+NOTCH4+." (PMID 32104513, 2020). "Multivariate analysis demonstrated that VM+, Notch4+, DLL4+, and/or KAI1/CD82+ specimens, and tumor size, LNM, distant metastasis (DM), and TNM stage, were independent prognostic factors for NSCLC." (PMID 30593175, 2018). "Our findings thus demonstrated that VM, Notch4, DLL4, and KAI1/CD82 were reliable biomarkers for NSCLC, and especially in predicting tumor metastasis and prognosis." (PMID 30593175, 2018). "In our study, multivariate analysis showed that VM, expression of Notch4, DLL4, and KAI1/CD82, as well as TNM stages, tumor size, DM, and LNM, were independent prognostic factors for NSCLC patients." (PMID 30593175, 2018). "In multivariate analysis, high VM, Notch4, DLL4 levels, tumor size, LNM, DM, TNM stage, and low KAI1/CD82 levels were potential to be independent prognostic factors for overall survival time (OST) in NSCLC patients." (PMID 30593175, 2018). "Overall, our findings indicate that complex interrelationships between the VM, Notch4, DLL4, and KAI1/CD82 in tumor progression." (PMID 30593175, 2018). "Although Notch4 was detected in both tumor and stromal compartments of NSCLC, the significance of Notch4 in NSCLC needs to be further determined." (PMID 28061457, 2017). "In our study, the GSI RO4929097 specifically targets NOTCH4 cleavage in anti-estrogen-treated cells and, thus, decreases BCSC activity in vitro (MFE and ALDH activity) and tumor initiation in vivo." (PMID 26387946, 2015).
tumor (continued). "miR-34c has been identified as a tumor suppressor because it has inhibitory activity in regulating self-renewal and EMT of breast CSCs through targeting Notch4." (PMID 26932376, 2014). "Blocking Notch4 specifically using RNA interference reduces the number of CD44+/CD24−/ESA+ cells, suppresses mammosphere formation and completely inhibits tumor initiation whereas inhibiting Notch 1 has only a modest effect." (PMID 23593654, 2013). "CD133-positive cells, isolated from the tumor, expressed stem cell markers including nestin, CD133, Ki67, Sox2, EFNB1, EFNB2, EFNB3, Cav-1, Musashi, Nucleostemin, Notch 2, Notch 4, and Pax6." (PMID 22995409, 2012). "To assess the fate of CMT167 oncospheres after orthotropic tumor formation, we isolated tumor cells from orthotopic tumors derived from these cultures and analyzed them for CD133+/Notch4+ cells." (PMID 22545096, 2012). "NOTCH2, NOTCH3, and NOTCH4 may act as oncogenes in cSCC, with studies showing high expression of NOTCH2 and NOTCH3 in cSCC tumor tissues." (PMID 39925808, 2025). "Together, the concurrent elevation of NOTCH4 and JAG2 supports sustained Notch signaling across diverse tumor subtypes, which in the case of JAG2 may be additionally related to the lack of inhibitory action by miRNAs." (PMID 41463075, 2025). "Providing a feedback mechanism, another study has found that the inhibition of Notch signaling or the suppression of Notch4/DLL3 leads to a decrease in endothelial markers and the function of tumor-derived endothelial cells following treatment with adriamycin or paclitaxel via VEGF receptor." (PMID 39092224, 2024). "Although analysis of both tumor models identified detectable levels of Notch4, in Calu-6 xenografts, the Notch4 signal was primarily localized to CD31-positive ECs, whereas in MDA-MB-231 xenografts, Notch4 expression did not overlap with the tumor vasculature." (PMID 38984877, 2024). "At early stages after tumor implantation, the vascular area was not changed, but perfusion decreased because of Notch4 inhibition, consistent with prior literature." (PMID 38984877, 2024). "Tumor models with low endothelial Notch4 expression responded poorly to Notch4 inhibition, even in cases in which tumor cells expressed Notch4." (PMID 38984877, 2024). "In the seven tumor types we tested, we observed that there was complete concordance between endothelial expression of Notch4 and responsiveness to E7011/6-3-A6 despite expression of Notch4 in other cell types in some tumors." (PMID 38984877, 2024). "The intensity of Notch4 expression in both non-neoplastic tissue and tumour tissue was determined using software Zen 2 (blue edition)." (PMID 37108670, 2023). "Notch4 signaling not just affects tumor cell biological behaviors but also is responsible for tumor angiogenesis." (PMID 37284062, 2023). "Tspan5 correlation analyses of TCGA tumour samples revealed that Tspan5 expression is positively correlated with the expression of ADAM10, Notch1, Notch2, Notch3, Notch4, Hey1, vimentin, N‐cadherin and Snail, whereas it is negatively correlated with E‐cadherin in HCC tissues." (PMID 33955149, 2021). "Increased levels of phosphorylated ERK, JNK, and P38 were observed in tumor with Notch4 overexpression compared with negative controls." (PMID 34988077, 2021). "Four Notch receptors have been associated with tumor growth (Notch1, Notch2, and Notch3), CSC regulation (Notch1, Notch2, Notch4), tumor invasion and metastasis (Notch1, Notch2, Notch3, Notch4), angiogenesis (Notch3), and drug resistance (Notch1 and Notch3)." (PMID 34207383, 2021). "Besides, GAS1 was identified as a novel NOTCH4 target gene in this work to contribute to cancer stemness, although GAS1 has long been regarded as a tumor suppressor gene due to its canonical role in inhibiting cell proliferation." (PMID 32104513, 2020).
tumor (continued). "Furthermore, we elucidate additional targets of FKBPL such as DLL4 and Notch 4, which in addition to CD44, are potentially involved in the multiple anti-tumour effects of FKBPL and its therapeutic peptide derivatives." (PMID 30975104, 2019). "Notch4 (a marker of Notch signaling pathway receptors), DLL4 (a marker of Notch signaling pathway ligands) and KAI1/CD82 (a suppressor gene of tumor metastasis) are all effective predictive factors for tumor metastasis." (PMID 30593175, 2018). "The positive rate of Notch4 expression in NSCLC was related to tumor size, LNM, DM, and TNM stage, but not patients’ age, gender, smoking, location, gross type, histological type, or tumor grade." (PMID 30593175, 2018). "VM and the expression of Notch4, DLL4, and KAI1/CD82 represent promising markers for tumor metastasis and prognosis, and maybe potential therapeutic targets for NSCLC." (PMID 30593175, 2018). "Therefore, inhibition of Notch4 activity can decrease the BCSC population, and suppress tumor initiation." (PMID 27793013, 2017). "Notch1 and Notch4 have been reported to have higher activity in the enriched breast CSC population, and inhibition of Notch signaling reduced stem cell activity in vitro and tumor formation in vivo." (PMID 25309874, 2014). "Wild type and Notch4−/− mice received intravenous injections of Cy3-lectin to highlight vessel perfusion, and tumor sections were immunostained with antibodies against CD31 to highlight overall tumor vasculature." (PMID 23601498, 2013). "We also found that host Notch4 is required for initial tumor vascular perfusion, but not vessel sprouting." (PMID 23601498, 2013). "Three weeks after transplantation, 100% of wild type hosts bore tumor whereas 86% of Notch4−/− hosts presented tumors, although this difference was not statistically significant." (PMID 23601498, 2013). "Our findings shed light on the role of Notch4, independent of other Notch receptors, in tumor-host interactions." (PMID 23601498, 2013). "Similarly, elevated levels of JAG2 and NOTCH4 in TNBC could further sustain Notch signaling, promoting aggressive tumor behavior and therapy resistance." (PMID 41463075, 2025). "Because Notch4 expression is not restricted to the tumor cells in the PKC GEMM, hence multiple cell lineages could be implicated in the observed phenotypes associated with the Notch4 loss." (PMID 36970723, 2022). "Therefore, enhanced tumor immunogenicity, activated antitumor immunity, and elevated PD-1, PD-L1, and CTLA4 expression could explain why NOTCH4-MUT tumors are more likely than NOTCH4-WT tumors to benefit from immunotherapy." (PMID 34284787, 2021). "In addition, we unexpectedly observed a tumor suppressor function of NOTCH4 in the non-TNBC cell line MCF-7, where forced activation of NOTCH4 induced cell differentiation and inhibited invasion." (PMID 32104513, 2020). "Although Notch4 acts as tumor activator in several tumors, it has been reported that Notch4 mRNA or protein expression is not significantly correlated to overall survival in both lung ADC and SCC and the role of Notch4 in lung SCC remains unclear." (PMID 30034624, 2018). "The tumor inhibition rate was evaluated, followed by the quantification of messenger ribonucleic acid (mRNA) and protein expression of notch signaling components NOTCH-1, NOTCH-3, NOTCH-4, JAG-1, DLL-4, Hes-1, and Hey-1 using quantitative polymerase chain reaction (qPCR)." (PMID 26762567, 2016). "For example, the NOTCH4 mutation observed in the metastasis from patient N°9 but not her primary tumor might impact in a near future the therapeutic decision, but no NOTCH4 inhibitor was included in the list of drugs tested here." (PMID 27028851, 2016). "Moreover, a critical role of Notch-4 rather than Notch1 has been recently shown for the survival of tumour-initiating cells." (PMID 24919951, 2014).